CD4 (CD4 molecule)
Diseases named in the same sentence as CD4 in open-access papers (continued):
Sharing a sentence is not in itself a finding about the gene and the disease.
DiGeorge syndrome (6 papers, 2018 to 2025). "We observed a strongly increased expression of PD1 on cTFHs, and to lesser extent also CXCR5− memory CD4+ T cells, in infants in both DiGeorge syndrome patients and healthy controls." (PMID 30083170, 2018). "PD1 expression further decreases later in life on cTFHs (linear regression, p = 0.04, R2 = 0.37), but not CXCR5− memory CD4+ T cells and CD4− T cells in DiGeorge syndrome." (PMID 30083170, 2018). "The population of CXCR5+ memory CD4+ T cells (cTFHs) was significantly expanded in patients with DiGeorge syndrome, but only healthy controls and not DiGeorge syndrome patients showed gradual increase of CXCR5 expression on cTFHs with age." (PMID 30083170, 2018). "We then show a much slower and gradual increase of PD1 expression in CXCR5− memory CD4+ T cells and CD4− T cells in healthy controls, but not DiGeorge syndrome patients, in older childhood and adolescence." (PMID 30083170, 2018). "We observed a significant decrease of PD1 expression on cTFHs (linear regression, p = 0.01, R2 = 0.78), but not CXCR5− memory CD4+ T cells or CD4− T cells in the first 5 years of life in patients with DiGeorge syndrome." (PMID 30083170, 2018).
endocarditis (6 papers, 2009 to 2022). Inflammation of the endocardium. "Patients with lower CD4 count, especially less than 200, have a higher risk of endocarditis, and more importantly, patients with endocarditis and lower CD4 counts have a much poorer prognosis." (PMID 20436855, 2009). "Conversely, animals depleted of CD4+ T cells fail to develop endocarditis, but arthritis remains unaffected, suggesting that T cells play a critical role in the development of endocarditis." (PMID 32266270, 2020). "No other variables including comorbid conditions, current receipt of antiretroviral therapy, pre-culture severity of illness, or CD4 count were significantly associated with endocarditis and none were associated with in-hospital mortality." (PMID 22040268, 2011).
eosinophilic esophagitis (6 papers, 2022 to 2026). Eosinophilic esophagitis (EoE) is a chronic, allergic disease of the esophagus characterized clinically by symptoms of esophageal dysfunction (including vomiting, dysphagia, feeding disorders, food impaction and abdominal pain) which persist after treatment with proton pump inhibitors (PPIs). "Esophageal biopsies from 20 patients with eosinophilic esophagitis were stained for major basic protein, galectin-10, CD4, CD8, CD16, and CD81 and analyzed by immunofluorescence confocal microscopy before and after topical corticosteroid treatment." (PMID 36808213, 2023). "Moreover, in a mouse model of eosinophilic esophagitis (EoE), RELMα induction by doxycycline (DOX) in the esophagus can promote epithelial cell hyperplasia and basal layer thickness, recruit activated CD4+ and CD4− T cell subsets, and exacerbate eosinophil accumulation." (PMID 36691020, 2023).
epithelial dysplasia (6 papers, 2013 to 2025). "The degree of epithelial dysplasia was significantly associated only with stromal counts of CD4+ and CD8+ cells." (PMID 27441558, 2016). "An increase in the rate of CD163+ TAM infiltration was observed in mild and moderate epithelial dysplasia, which positively correlated with the rate of intraepithelial CD4+ Th cell infiltration." (PMID 26242181, 2015).
esophageal adenocarcinoma (6 papers, 2020 to 2022). A malignant tumor with glandular differentiation arising predominantly from Barrett mucosa in the lower third of the esophagus. "This was consistent with a study on esophageal adenocarcinoma which showed a strong co-expression between VISTA and CD4." (PMID 33505908, 2020). "Recently, PD-1H was reported to be expressed with CD68 and CD4 in most cases of esophageal adenocarcinoma (EAC) and to have no reliable coexpression with CD8." (PMID 34950702, 2021).
hairy leukoplakia (6 papers, 2008 to 2024). "In Shiboski’s study, hairy leukoplakia was directly related with both decrease in CD4+ count and smoking." (PMID 25745611, 2015). "The lateral sides of the tongue were predominantly affected in all cases of oral hairy leukoplakia and they presented with the lowest mean CD4+ cell count (97.89/mm3)." (PMID 20418994, 2010). "One patient had a hairy leukoplakia and his CD4 count was 223/μL." (PMID 18416821, 2008).
hantavirus infection (6 papers, 2015 to 2024). "It is currently believed that CD8 + T cells, CD4 + T cells, Treg cells, and B cells are involved in the immune response caused by Hantavirus infection, and serum cytokine expression has also changed." (PMID 35459229, 2022). "Specifically for hantavirus infections, activation of CD4+ T cells have been shown to be instrumental in viral control and improved clinical outcome." (PMID 28640917, 2017). "In addition, upregulation of PD-1 in hantavirus infection on CD4+ lymphocytes in the early stage of the disease was previously reported." (PMID 38792573, 2024).
hay fever (6 papers, 2009 to 2023). "More recently, reduced CD4 T cell responses after exposure to allergens has been reported in seasonal pollen allergy." (PMID 33616085, 2021).
Headache (6 papers, 2009 to 2024). Cephalgia, or pain sensed in various parts of the head, not confined to the area of distribution of any nerve. "Decreased CD4 T cells independently predicted COVID-associated headaches, with elevated IL-6 levels noted in the dominant-headache group (p = 0.040)." (PMID 39274228, 2024). "In addition to younger age, lower CD4+ T cells count was associated with a higher risk of COVID-related headache." (PMID 39274228, 2024). "Decreased CD4+ T cells were found as an independent predictor of COVID-associated headache." (PMID 39274228, 2024). "Patients with headache had significantly lower CD4+ T cells (p = 0.038) and lower serum levels of fasting glucose (p = 0.008)." (PMID 39274228, 2024). "Implementing a targeted screening of HIV patients with low body mass index, CD4 count < 100 cells, having headaches; and treatment for asymptomatic cryptococcal disease should be considered among inpatients infected by HIV in DRC." (PMID 33425177, 2020). "We identified numerous genes associated with headache, both temporal and other types: POFUT2 in CD4 cells, and SLC35F6, HTD2, ZNF708, KLRC4-KLRK1 and JMJD7 in CD8 cells." (PMID 30037347, 2018).
hemorrhage (6 papers, 2012 to 2024). Loss of blood from the vascular compartment to the exterior or into nonvascular body space as a result of rupture or severance of the blood vessels. "Thus, the pathogenic role of CD4+ T lymphocytes in IRI may account for the immune protection in the PATG group following hemorrhage." (PMID 23009382, 2012). "In the present study, CCMSympt patients (87% with lesional hemorrhage and 13% with seizure crisis) had a higher frequency of (CD4+ and CD8+) T lymphocytes expressing TLR4 gated in a region containing larger and more granular cells than CCMAsympt patients." (PMID 35109870, 2022). "The contents of IL-2, IL-4 and TIPE2 produced by splenic CD4+ T lymphocytes were decreased following trauma-hemorrhage, which were normalized by administrations of E2 or PPT, but not DPN or G1." (PMID 33820957, 2021). "The aim is to investigate that 17β-estradiol (E2)/estrogen receptors (ERs) activation normalizes splenic CD4 + T lymphocytes proliferation and cytokine production through inhibition of endoplasmic reticulum stress (ERS) following hemorrhage." (PMID 33820957, 2021).
herpes simplex encephalitis (6 papers, 2011 to 2023). Herpes simplex virus encephalitis (HSE) is caused by the infection of the central nervous system by Herpes simplex virus (HSV) that could have a devastating clinical course and a potentially fatal outcome particularly with delay or lack of treatment. "For example, B. fragilis expresses the capsular polysaccharide A (PSA) to induce CD4+ T-cell-dependent immune response and activates immunomodulatory IL-10, exhibiting anti-inflammatory effects during herpes simplex encephalitis." (PMID 37235443, 2023). "Macrophages, CD4+ and CD8+ T cells are present in perivascular infiltrates close to and in contact with HSV-infected cells in areas of massive myelin loss necrosis in the brainstem of mice with HSV encephalitis." (PMID 23391218, 2013). "Atypical clinical presentations of HSV encephalitis have been described in patients receiving steroids, and also occur in 2% of patients infected with human immunodeficiency virus (HIV) with neurological symptoms, usually in association with CD4 T cell counts <200 cells/μL." (PMID 21314934, 2011). "PSA reduces brain stem inflammation and prevents fatal herpes simplex encephalitis (HSE) by binding to enteric-resident plasma blasts and inducing secretion of IL-10 and gamma-interferon (IFNγ) by CD4+T cells and CD8+T cells." (PMID 36992112, 2023). "It was also reported that there was significant difference in CD4:CD8 cells ratio in CSF between anti-N-methyl-d-aspartate receptor AE and herpes simplex virus encephalitis, while this marker need verified widely in more other types of AE and IE." (PMID 37332019, 2023).
hypercoagulation (6 papers, 2016 to 2025). "This therapeutic approach resulted in transient lower microbial translocation, lower systemic immune activation, lower viral replication, better preservation of mucosal CD4+ T cells and lower levels of hypercoagulation biomarkers throughout acute SIV infection." (PMID 26764484, 2016). "RFX+SFZ administration during acute SIVsab infection of PTMs resulted in: significantly lower microbial translocation, lower systemic immune activation, lower viral replication, better preservation of mucosal CD4+ T cells and significantly lower levels of hypercoagulation biomarkers." (PMID 26764484, 2016). "As the HIV virus infects CD4 lymphocytes, HIV positive patients may be more prone to developing microparticles and therefore enhancing the hypercoagulable state." (PMID 32571345, 2020).
Hypocalcemia (6 papers, 2013 to 2023). An abnormally decreased calcium concentration in the blood. "Clinical examinations related to 22q11.2DS showed that the mother had hypocalcemia and low percentages of CD4 + T helper cells." (PMID 31297990, 2019). "However, the extended laboratory examinations on this mother showed some moderate abnormalities, including hypocalcemia, hypophosphatemia, and low percentage of CD4 + T helper cells." (PMID 31297990, 2019). "An unexpected finding was that the number of peripheral CD8+ T cells in SLE patients with hypocalcemia was higher than that in SLE patients with normal calcium level, while CD4+ T cells did not change." (PMID 35757710, 2022).
keratitis (6 papers, 2015 to 2023). A corneal disease that is characterized by inflammation of the cornea. "Recently, it has been shown that Tregs can acquire pathogenic effector T cell phenotype and secret IFN-γ, and their adoptive transfer can cause similar severity of keratitis compared with CD44hi effector CD4 T cells." (PMID 32877681, 2020). "Given that HSV-1 keratitis is an immunopathological disease, with pro-inflammatory cytokine production and corneal infiltration by neutrophils and CD4+ T-cells, one might have expected to find that sex differences in immune responses would affect disease severity." (PMID 37319284, 2023).
kidney injury (6 papers, 2012 to 2022). Trauma to the kidney. "Because immune cells infiltrate into the kidney and secrete large amounts of cytokines during cisplatin-induced kidney injury, we next performed IHC staining with antibodies against F4/80 and CD4 to detect macrophages and CD4+ T cells, respectively." (PMID 35469348, 2022). "As compared to mice injected with aristolochic acids alone, more severe acute kidney injury was observed after CD4+ or CD8+ T-cells depletion." (PMID 29593222, 2018). "The association between the number of CD4+CD25+ cells and clinical parameters were examined in patients with primary MHTN related kidney injury." (PMID 27278520, 2016). "Additional studies are necessary to demonstrate functional deficits or other biological properties of CD4+CD25+ cells in primary MHTN related kidney injury." (PMID 27278520, 2016). "The reported CD4+/CD8+ T lymphocyte infiltrate in the setting of treatment with immunotherapy raises the hypothesis of whether the effector T cells were involved in provoking kidney injury." (PMID 28105370, 2017).
knee osteoarthritis (6 papers, 2016 to 2025). "It is well stated by the current literature that the amount of CD4 T cells is increased in the peripheral blood in the case of knee osteoarthritis." (PMID 31209645, 2019). "Recently, we observed IL‐6‐secretion by CD4+ T cells from the stromal vascular fraction (SVF) of the infrapatellar fat pad (IFP) of knee osteoarthritis patients directly ex vivo." (PMID 29283192, 2018). "In this study, we investigated IL‐6+CD4+ T cells present in the SVF of the IFP in knee osteoarthritis patients." (PMID 29283192, 2018). "To further investigate T cell phenotypes that may attribute to the pathogenesis of knee osteoarthritis, we characterized peripheral blood, synovial tissue, and infrapatellar fat pad T cells based on their coreceptor expression into CD4+, CD8+, and DN T cell subsets." (PMID 28070192, 2016).
leukoplakia (6 papers, 2010 to 2024). A white patch or plaque on a mucous membrane that cannot be characterized clinically or pathologically as any other disease. "CD4+ cells infiltrate mainly to the lamina propria of oral leukoplakias; as soon as these lesions transform its infiltrative capacity to turn into carcinoma, mucosa increases the recruitment of CD4+ cells." (PMID 32149076, 2020). "In the present study, we evaluated the relationship between infiltrated T cells and the polarization of TAMs in oral leukoplakia and found a positive correlation between the numbers of CD4+ T cells and CD163+ macrophages." (PMID 26242181, 2015). "Intriguingly, the infiltrated CD4+ T cells in oral leukoplakia consisted of CXCR3+ and CCR5+ Th1 cells, a major IFN-producing cell type, and CCR4+ Th2 cells were rare in the lesion." (PMID 26242181, 2015). "Both CD4+ and CD8+ (data not shown) T cells were observed in the subepithelial stroma of leukoplakia." (PMID 26242181, 2015).
low grade glioma (6 papers, 2020 to 2023). A grade I or grade II glioma arising from the central nervous system. "Among the hub genes, PTPRN expression was reported to significantly restraint the infiltrating levels of CD4 T cells, B cells, macrophages, neutrophil, and dendritic cells in low grade glioma." (PMID 36713370, 2022). "Research suggested that the expression of COL1A1 was significantly associated with the infiltration level of immune cells, such as CD4 + T cells, CD8 + T cells, dendritic cells and neutrophils in low grade gliomas (LGG)." (PMID 37415178, 2023). "In low-grade glioma, MEG3 expression has been negatively correlated with the amounts of infiltrating B, CD8+ T and CD4+ T cell populations as well as macrophage, neutrophil, and dendritic cells." (PMID 37907501, 2023). "In low grade glioma (LGG), HIST1H2BK was inversely related to tumor purity, and was positively correlated with B cells, CD4+ T cells, CD8+ T cells, neutrophils, macrophages and dendritic cells." (PMID 32457836, 2020).
memory impairment (6 papers, 2018 to 2025). "Similarly, studies have also shown that elevated circulating Neu5Ac level is associated with accelerated immune exhaustion (CD4+ T-cell compartment) and recognition-memory impairment." (PMID 37771765, 2023). "Effector memory CD4 T cells were correlated with memory impairment in AD patients." (PMID 40927314, 2025). "Surprisingly, CD4 T-lymphocytes are required for normal learning and memory in the brain, because removal of the dcLN disrupted T-cells circulation and induced learning and memory impairments in mice." (PMID 30360353, 2018). "The pure manifestation of memory impairment without affecting other neuropsychological functions are likely associated with elevated CD4+ T-cells, CD8+ T-cells and CD19+ B-cells that might bear clues for the pathogenesis of memory dysfunction in these AE." (PMID 36247087, 2022).
morbid obesity (6 papers, 2019 to 2024). An excess of body weight, normally defined as an individual with a body mass index greater than 35 or a body weight greater than one hundred percent of ideal body weight. "Different peripheral blood immune cell subsets including CD4+ T cells, B cells, NK cells, as well as monocytes have been shown to be highly influenced by morbid obesity." (PMID 37266430, 2023). "Illustration of UMAP density plots revealed shifts in the major immune cell populations of patients with morbid obesity compared to the CTRL cohort conspicuously visible in CD4+ T cells, granulocytes and monocytes." (PMID 37266430, 2023). "Moreover, both the number and the percentage of circulating CD4+ Treg cells within CD4+ T cells are reduced in adults with morbid obesity." (PMID 38397455, 2024). "In a previous article, we reported that significant weight loss in subjects with morbid obesity did not alter either the proportion of adipose tissue T lymphocytes (into the ensemble of non-adipose cells) or the CD4+:CD8+ ratio." (PMID 38053998, 2023). "Moreover, compared to the control population, patients with morbid obesity showed a perturbed CD4+ T cell compartment, characterized by a strongly elevated CD127+ memory T cell subset and decreased naïve T cells, which was not recovered within 9 – 11 months post-surgery." (PMID 37266430, 2023). "T cells (CD3+) including CD4+ T helper cells and CD8+ cytotoxic T cells as well as NK cells (Lin-, CD56+) tend to be slightly decreased in patients with morbid obesity." (PMID 37266430, 2023). "Moreover, younger age, chronic comorbid conditions, morbid obesity, high-dose steroid use, hematopoietic stem cell therapy, lower levels of CD4+T specific cells and a lack of early antiviral therapy were also regarded as independent risk factors for severe disease, according to prior reports." (PMID 31849894, 2019).
myeloid sarcoma (6 papers, 2006 to 2024). A tumor mass composed of myeloblasts or immature myeloid cells. "Differential diagnoses of BPDCN include myeloid sarcoma, myelomonocytic leukemia (which can express CD4, CD56 and CD123), mature plasmacytoid dendritic cell proliferation (MPDCP) and Merkel cell carcinoma (MCC) which are all excluded in this case by appropriate immunohistochemistry study." (PMID 39210931, 2024). "Flow cytometry showed an immature cell population (CD45 dim) that was negative for CD34, CD56, CD117, and MPO; strongly positive for CD4; and variably positive for CD10, CD33, HLA‐DR, CD68, CD123, and E‐cadherin, consistent with myeloid sarcoma (MS)." (PMID 31788302, 2019). "Moreover, the combination of CD4, CD56, and CD123 can occur in AML and myeloid sarcoma with monocytic differentiation." (PMID 38194088, 2024). "Fine-needle aspiration with flow cytometry revealed expression of HLA-DR and CD13 but a lack of CD2, CD3, CD4, CD8, suggesting the diagnosis of chloroma." (PMID 16623775, 2006).